NCLN (nicalin)
Description:
Component of the multi-pass translocon (MPT) complex that mediates insertion of multi-pass membrane proteins into the lipid bilayer of membranes. The MPT complex takes over after the SEC61 complex: following membrane insertion of the first few transmembrane segments of proteins by the SEC61 complex, the MPT complex occludes the lateral gate of the SEC61 complex to promote insertion of subsequent transmembrane regions. May antagonize Nodal signaling and subsequent organization of axial structures during mesodermal patterning, via its interaction with NOMO (By similarity).
Synonyms: NET59
Tractability: Antibody: UniProt predicts a signal peptide or a membrane-spanning region. PROTAC: ubiquitination databases record sites on it; its protein half-life has been measured.
Gene: Protein-coding gene on chromosome 19 (3,185,563 to 3,209,575, forward strand). Ensembl gene ENSG00000125912.
Subcellular location: Endoplasmic reticulum membrane
Subcellular location (Human Protein Atlas): Lipid droplets; Nucleoplasm
Gene Ontology:
Molecular function: protein binding; ribosome binding
Biological process: multi-pass transmembrane protein insertion into ER membrane; protein stabilization; regulation of protein complex stability; regulation of protein-containing complex assembly; determination of left/right asymmetry in lateral mesoderm; negative regulation of nodal signaling pathway; regulation of signal transduction
Cellular component: endoplasmic reticulum membrane; membrane; multi-pass translocon complex; protein-containing complex
Genetic constraint (gnomAD): Loss-of-function variants: 33 observed, 54.37 expected, observed/expected ratio (o/e) 0.61, 90% interval 0.46 to 0.81. The synonymous counts are far from expectation, so gnomAD's model fits this gene poorly and the ratio says little. Missense variants: 690 observed, 685.56 expected, observed/expected ratio (o/e) 1.01, 90% interval 0.94 to 1.07. Synonymous variants: 383 observed, 301.98 expected, observed/expected ratio (o/e) 1.27, 90% interval 1.17 to 1.38.
Homologues: Orthologues: chimpanzee NCLN (99% identical), dog NCLN (95% identical), mouse Ncln (93% identical), rat Ncln (93% identical), macaque NCLN (93% identical), pig NCLN (93% identical), guinea pig NCLN (93% identical), tropical clawed frog ncln (82% identical), zebrafish ncln (75% identical), Drosophila melanogaster CG4972 (34% identical), Caenorhabditis elegans nra-2 (29% identical).
Diseases named in the same sentence as NCLN in open-access papers:
NCLN is named in the same sentence as 4 diseases in open-access papers, as found by Europe PMC text mining. Sharing a sentence is not in itself a finding about the gene and the disease. The quoted sentences say what the papers report.
lymphoma (1 paper, 2016). A malignant (clonal) proliferation of B- lymphocytes or T- lymphocytes which involves the lymph nodes, bone marrow and/or extranodal sites. "Consistent with our observation in U2OS cells, expression of both clock genes correlated inversely with MYC levels in human lymphoma (Pearson coefficient −0.61 and −0.37 for BMAL1 and CLOCK, respectively; n=102), whereas MYC-activated genes such as NCL and NCLN showed a positive correlation." (PMID 27339797, 2016).
renal fibrosis (1 paper, 2021). A final common manifestation of a wide variety of chronic kidney diseases characterized by glomerulosclerosis and tubulointerstitial fibrosis. "(A) Decreased expression of HIST1H1B, a histone protein (B) increased expression of ACTA2, a marker of renal fibrosis, (C) decreased expression of NCLN, a part of the endoplasmic reticulum, and (D) decreased expression of CISD2, which is involved in mitochondrial autophagy." (PMID 33687326, 2021).
NCLN also shares sentences with these, for which no sentence is quoted: cancer (1 paper); tumor (1).